MARK3 (microtubule affinity regulating kinase 3)
Description:
Serine/threonine-protein kinase. Involved in the specific phosphorylation of microtubule-associated proteins for MAP2 and MAP4. Phosphorylates the microtubule-associated protein MAPT/TAU. Phosphorylates CDC25C on 'Ser-216'. Regulates localization and activity of some histone deacetylases by mediating phosphorylation of HDAC7, promoting subsequent interaction between HDAC7 and 14-3-3 and export from the nucleus. Regulates localization and activity of MITF by mediating its phosphorylation, promoting subsequent interaction between MITF and 14-3-3 and retention in the cytosol. Negatively regulates the Hippo signaling pathway and antagonizes the phosphorylation of LATS1. Cooperates with DLG5 to inhibit the kinase activity of STK3/MST2 toward LATS1. Phosphorylates PKP2 and KSR1.
Synonyms: cTAK1; Par-1a; KP78; PAR1A; VIPB
Tractability: Small molecule: a structure with a bound ligand is known; a high-quality ligand is known; it has a high-quality binding pocket; it belongs to a druggable protein family. Antibody: UniProt places it where antibodies can reach, with high confidence; its Gene Ontology location is reachable by antibodies, with high confidence. PROTAC: it is named in the literature on targeted protein degradation; ubiquitination databases record sites on it; its protein half-life has been measured; a small molecule that binds it is known.
Target class: Protein Kinase; Kinase; CAMK protein kinase group; CAMK protein kinase MARK subfamily; CAMK protein kinase CAMK1 family; Enzyme
Gene: Protein-coding gene on chromosome 14 (103,385,361 to 103,503,831, forward strand). Ensembl gene ENSG00000075413.
Subcellular location: Cell membrane; Cell projection, dendrite; Cytoplasm
Pathways (Reactome):
Disease: Paradoxical activation of RAF signaling by kinase inactive BRAF; Signaling by BRAF and RAF1 fusions; Signaling by RAF1 mutants; Signaling by high-kinase activity BRAF mutants; Signaling by moderate kinase activity BRAF mutants; Signaling downstream of RAS mutants
Signal Transduction: MAP2K and MAPK activation; Negative regulation of MAPK pathway; RAF activation
Developmental Biology: Transcriptional and post-translational regulation of MITF-M expression and activity
Gene Ontology:
Molecular function: protein binding; protein phosphatase binding; protein serine kinase activity; protein serine/threonine kinase activity; tau-protein kinase activity; tau protein binding; ATP binding; protein kinase activity
Biological process: negative regulation of hippo signaling; negative regulation of protein localization to nucleus; protein phosphorylation; regulation of G2/M transition of mitotic cell cycle; intracellular signal transduction; microtubule cytoskeleton organization
Cellular component: cytoplasm; dendrite; extracellular exosome; plasma membrane; cytosol
Genetic constraint (gnomAD): Loss-of-function variants: 29 observed, 54.13 expected, observed/expected ratio (o/e) 0.54, 90% interval 0.4 to 0.73. The upper end of that interval is the gene's LOEUF score, 0.73, which puts it in group 2 of 6, group 1 being the genes least tolerant of losing a copy. Missense variants: 655 observed, 780.18 expected, observed/expected ratio (o/e) 0.84, 90% interval 0.79 to 0.9. Synonymous variants: 257 observed, 284.43 expected, observed/expected ratio (o/e) 0.9, 90% interval 0.81 to 1.
Homologues: Orthologues: chimpanzee MARK3 (99% identical), dog MARK3 (99% identical), rabbit MARK3 (98% identical), guinea pig MARK3 (97% identical), pig MARK3 (96% identical), mouse Mark3 (96% identical), rat Mark3 (95% identical), macaque MARK3 (95% identical), tropical clawed frog mark3 (92% identical), zebrafish mark3b (87% identical), zebrafish mark3a (72% identical). Paralogues in human: MARK1 (74% identical), MARK2 (64% identical), MARK4 (63% identical).